CST3 (cystatin C)
Diseases named in the same sentence as CST3 in open-access papers (continued):
Sharing a sentence is not in itself a finding about the gene and the disease.
brain hemorrhage (3 papers, 2008 to 2014). "In hereditary cystatin C amyloid angiopathy, a cystatin C variant is deposited in arterial walls and cause brain hemorrhage in young adults." (PMID 23629649, 2013). "Given its association with the severity of CMBs, cystatin C levels could help stratify the risk for intracranial hemorrhage more accurately." (PMID 24925313, 2014). "In hereditary cystatin C amyloid angiopathy (HCCAA), a mutation in the cystatin C gene produces a protein variant, L68Q cystatin C, which rapidly forms oligomers and amyloid deposition in the brain arteries, resulting in brain hemorrhage and death in early adult life." (PMID 23629649, 2013). "This work focuses on the L68Q mutation in the cystatin C gene which causes hereditary cystatin C amyloid angiopathy (HCCAA), an autosomal dominant disease with high penetrance in contemporary Icelanders, manifest by lethal brain hemorrhages in young normotensive adults." (PMID 18566660, 2008). "Hereditary cystatin C amyloid angiopathy (HCCAA) is an autosomal dominant disease with high penetrance, manifest by brain hemorrhages in young normotensive adults." (PMID 18566660, 2008).
Cachexia (3 papers, 2016 to 2025). Severe weight loss, wasting of muscle, loss of appetite, and general debility related to a chronic disease. "The patient was treated with nephrotoxic agents; therefore cystatin C was assessed to determine if cachexia was resulting in a falsely low serum creatinine." (PMID 27293926, 2016). "Although not directly analyzed in this study, cachexia is often associated with low skeletal muscle mass, which we measured using the creatinine-to-cystatin C ratio (CCR)." (PMID 41195263, 2025). "Given the patient's cachexia, creatinine was suspected to be an unreliable marker of GFR, therefore prompting cystatin C to be checked in order to assist with dosing and monitoring of foscarnet and other antimicrobials." (PMID 27293926, 2016).
cardiac arrest (3 papers, 2013 to 2016). Cessation of breathing and/or cardiac function. "Our observation of an association between biphasic Cystatin C levels and in-hospital mortality can be explained by an analysis of ischemia-reperfusion injuries of heart and brain in cardiac arrest." (PMID 27256246, 2016). "Increased injury biomarkers within a few hours of cardiac arrest, including urinary cystatin C and plasma and urinary Neutrophil-Gelatinase-Associated-Lipocalin (biomarker-positive, creatinine-negative patients) also indicated AKI in these patients." (PMID 23327106, 2013).
carotid atherosclerosis (3 papers, 2018 to 2026). A thickening and loss of elasticity of the walls of carotid arteries that occur with formation of atherosclerotic plaques. "The reduced GFR influenced the prevalence of carotid atherosclerosis only when calculated by the CKD-EPI formula using cystatin C as a serum marker." (PMID 30278805, 2018). "Age, albuminuria, and GFR (estimated by the formula CKD-EPI using cystatin C) influenced the prevalence of carotid atherosclerosis." (PMID 30278805, 2018).
cerebral aneurysm (3 papers, 2016 to 2020). "One of the strengths is that, in other models of cystatin C, a deficiency in aortic and cerebral aneurysm has been demonstrated and the patient group mentioned was excluded in our study to obtain reliable results." (PMID 33224650, 2020). "A cerebral aneurysm was created surgically in mice, and it was demonstrated by immunohistochemistry methods that after three months of follow-up, the levels of cathepsin B, S, and K in the aneurysmal tissues increased and the cystatin C level decreased." (PMID 33224650, 2020). "Moreover, cystatin C regulates the extracellular matrix turnover, and an imbalance between cysteine cathepsins and cystatin C could promote the progression of cerebral aneurysms." (PMID 29930507, 2018).
chronic kidney failure (3 papers, 2021 to 2024). "BKPyV viruria was significantly linked to pre-existing chronic kidney failure (p = 0.019), creatine > 100 μmol/L (p < 0.001), and cystatin c > 1.11 mg/L (p = 0.021), respectively." (PMID 34205390, 2021). "Interestingly, BKPyV viruria was significantly linked to preexisting chronic kidney failure (p = 0.019), creatine > 100 μmol/L (p < 0.001), and cystatin c > 1.11 mg/L (p = 0.021), respectively." (PMID 34205390, 2021).
coronary atherosclerosis (3 papers, 2012 to 2025). Atherosclerosis of the coronary vasculature. "Mendelian randomization (MR) analyses were conducted to assess the causal effect of cystatin C level on coronary atherosclerosis risk." (PMID 37817071, 2023). "We used Mendelian Randomization (MR) analysis to evaluate causality of serum cystatin C level on coronary atherosclerosis by using genetic variants as instrumental variables for risk factors." (PMID 37817071, 2023). "Given that it is difficult to evaluate the causality of serum cystatin C level on coronary atherosclerosis for the potential confounding interference that exist in observational studies." (PMID 37817071, 2023). "Cystatin C levels had a causal effect on an increased risk of coronary atherosclerosis at the genetic level." (PMID 37817071, 2023). "In two-sample MR analyses, we found a potential association between genetic determinants of cystatin C level and coronary atherosclerosis." (PMID 37817071, 2023). "Furthermore, serum cystatin C levels had a causal effect on an increased risk of coronary atherosclerosis at the genetic level." (PMID 37817071, 2023). "In addition, we found that serum cystatin C levels had a causal effect on an increased risk of coronary atherosclerosis at the genetic level." (PMID 37817071, 2023). "Current research finds that serum cystatin C levels were associated with coronary atherosclerosis." (PMID 37817071, 2023). "Furthermore, cystatin C also contributes to cardiovascular mortality through mechanisms extending beyond cerebrovascular effects, including direct roles in coronary atherosclerosis and myocardial injury." (PMID 40941489, 2025). "The leave-one-out sensitivity analysis showed that the association between serum cystatin C level and coronary atherosclerosis was not substantially driven by any individual SNP." (PMID 37817071, 2023).
diabetic foot ulcers (3 papers, 2016 to 2023). "Our study also proposed that cystatin C can be used as a predictor of diabetic foot ulcers." (PMID 36545333, 2022).
emphysema (3 papers, 2016 to 2025). "OR = 0.28) and the cathepsin S/cystatin C ratio (p = 0.002, OR = 0.82) were the strongest factors associated inversely with the presence of severe emphysema." (PMID 27994288, 2016). "However, the level of CST3 in serum in patients with emphysema caused by smoking and in elderly men with respiratory disorders and lung diseases was significantly increased." (PMID 34952961, 2021). "It is also intriguing that plasma cathepsin S and cathepsin S/cystatin C ratios tend to be higher in patients with mild airflow limitation and emphysema than those in patients with severe impairment." (PMID 27994288, 2016). "Thus, plasma cathepsin S levels, but not cystatin C levels, were significantly increased in patients with AR and with mild COPD when compared with patients with severe airflow limitation and emphysema." (PMID 27994288, 2016).
glaucoma (3 papers, 2023 to 2025). Increased pressure in the eyeball due to obstruction of the outflow of aqueous humor. "Among them, GADD45B, FZD1, EFNA1, LTBP3, and CST3 have been reported to potentially play a role in the development of both AD and glaucoma." (PMID 40988281, 2025). "For glaucoma, PTGDS, GSTP1, SPD1, and CST3 were expressed significantly higher in almost all tissues; CRP, ALB, and TTR were markedly increased in the liver; MBP and TF exhibited high expression in the brain." (PMID 37052519, 2023).
haemorrhage (3 papers, 2008 to 2023). "Serum cystatin C and urinary NGAL were significantly raised in women with pre-eclampsia, while only urinary NGAL in women with ante-partum hemorrhage and eclampsia." (PMID 36694779, 2023).
Hyperbilirubinemia (3 papers, 2023 to 2024). An increased amount of bilirubin in the blood. "Multiple studies have demonstrated that CST3 plays a protective role in the brain, possibly through pathways associated with autophagy or inhibition of cysteine proteases; however, the relationship between CST3 and hyperbilirubinemia, and the function of exosomes in hyperbilirubinemia is unclear." (PMID 39434773, 2024). "Effects of exogenous CST3 to enhance viability and autophagy of neurocytes suggest that CST3 might serve as a potential drug for the treatment of hyperbilirubinemia." (PMID 37854583, 2023). "To further explore the mechanism of the protective effect of CST3 on hyperbilirubinemia, we studied the autophagy pathway and found that CST3 could enhance autophagy flux in HT22 cells and the protective effect could be inhibited by autophagy inhibitor bafilomycin A1." (PMID 37854583, 2023). "To investigate the mechanism of the protective effect of CST3 on hyperbilirubinemia, we measured the solubility of UCB, and found that CST3 could increase the solubility of UCB in a cell-free system, but it did not have significant difference compared with CTL (CST3 solvent, PBS)." (PMID 37854583, 2023).
hypercoagulability (3 papers, 2018 to 2025). "All biomarkers showed a good association with D-Dimer levels, and consequently, with hypercoagulability status, and cystatin C showed the best association among them." (PMID 29694626, 2018). "This could partially explain the better association of this renal biomarker with higher D-Dimer levels, since cystatin C could detect a decline of renal function, and consequently a hypercoagulability state, that is not detected by other biomarkers." (PMID 29694626, 2018).
hyperphosphatemia (3 papers, 2016 to 2023). Abnormally high level of phosphate in the blood. "Participants with hypocalcemia, hyperphosphatemia, and hyperparathyroidism all had increased levels of Cystatin C and BUN compared to children with normal values for the same marker of mineral metabolism." (PMID 36819194, 2022). "The hyperphosphatemia was likely due to reduced renal clearance and was correlated with higher Cystatin C levels as a measure of reduced glomerular filtration in these children." (PMID 36819194, 2022).
hypertrophy (3 papers, 2011 to 2019). Hypertrophy is the increase in the volume of an organ or tissue due to the enlargement of its component cells. "Moreover, the cystatin C concentration predicts all-cause and CVD mortality in patients with CKD, and cystatin C might be a biomarker of cardiac dysfunction and hypertrophy." (PMID 29513723, 2018). "In case of cardiac hypertrophy in spontaneously hypertensive rats (SHRs), it was demonstrated that TsIIA may inhibit cardiac hypertrophy by inhibiting the cystatin c (Cys-C)/Wingless (Wnt) signaling pathway." (PMID 31338034, 2019). "Furthermore, in patients with hypertension, cystatin C is related to the left ventricular mass and could be a marker of cardiac hypertrophy." (PMID 29513723, 2018).
IgA nephropathy (3 papers, 2022 to 2024). "The levels of serum creatinine (Scr), blood urea nitrogen (BUN), 24-h urine protein, and cystatin C (CysC) in the IgA nephropathy group were significantly higher than those in the healthy control (HC) group, with a statistical significance (P < 0.05)." (PMID 35872757, 2022). "Five SNPs used for genetic prediction of PCa, 1 for IgA nephropathy, 4 for urinary albumin excretion, 1 for potassium in urine, 3 for sodium creatine in urine, 2 for serum creatinine (eGFRcrea), and 1 for serum cystatin C (eGFRcys) were excluded due to the presence of confounding factors.." (PMID 38348104, 2024). "Univariate logistic regression analysis showed that MAP, proteinuria, urine osmolality, blood albumin, baseline serum creatinine, blood uric acid, cystatin C, and baseline eGFR were predictive indicators of tubular atrophy/interstitial fibrosis in IgA nephropathy." (PMID 38426107, 2024).
infertile (3 papers, 2022 to 2024). "CST3 has been reported to alter sperm motility in infertile patients on chronic hemodialysis." (PMID 38028760, 2023).
liver cancer (3 papers, 2024 to 2025). An epithelial or non-epithelial malignant neoplasm that arises from the liver. "Lastly, in addition to cystatin C, apolipoprotein B, phosphate, monocyte count, males and those of smoking history were associated with liver cancer." (PMID 38263244, 2024). "In contrast, the large UK Biobank study, with over 241,000 participants, identified associations between higher cystatin C levels and mortality from specific cancers, including lung, blood, brain, esophageal, breast, and liver cancers." (PMID 39859953, 2024).
liver failure (3 papers, 2017 to 2025). A liver disease characterized by the liver losing or has lost all of its function. "The addition of cystatin C and further biomarkers in the NMR constellation (valine, myo-inositol) seem to improve the bias and accuracy of GFR estimations in decompensated liver failure." (PMID 37003973, 2023).
meningioma (3 papers, 2004 to 2021). A generally slow growing tumor attached to the dura mater. "We have also observed an up regulation of CST3 in meningioma tumour samples when compared to control tissues." (PMID 34055594, 2021). "CST3 is an inhibitor of cysteine proteases and has been reported to have a positive alteration in high-grade meningiomas." (PMID 34055594, 2021). "The corresponding transcript levels were validated for PACS1, LAMP2, HTRA1 and CST3 in meningioma tissue." (PMID 33167358, 2020). "For the meningioma tissue samples, we observed overexpression of VIM, CST3 and CLU." (PMID 34055594, 2021). "Following RT-qPCR, we identified a significant reduction in relative expression for CST3, LAMP2, PACS1 and HTRA1 in grade III meningioma compared with grade I compatible with our hypothesis that increased abundance of these proteins in the tumour originates from the blood circulation." (PMID 33167358, 2020). "Notably, we derived a plasma signature of 21 discordantly expressed genes showing positive changes in protein but negative in transcript levels of high-grade meningiomas, including the validated genes CST3, LAMP2, PACS1 and HTRA1, suggesting the acquisition of these proteins by tumour from plasma." (PMID 33167358, 2020).
Multiple Organ Failure (3 papers, 2020 to 2022). A progressive condition usually characterized by combined failure of several organs such as the lungs, liver, kidney, along with some clotting mechanisms, usually postinjury or postoperative. "In this study, elevated cystatin C levels were associated with higher IL-6 levels and comorbidities, which may illustrate an association between kidney injury and cytokine storm syndrome or multiple organ failure." (PMID 33828483, 2021). "Compared to creatinine, cystatin C may be a better biomarker of kidney function in patients with ARDS and therefore identify patients with multiple organ failure at higher risk of death." (PMID 32653023, 2020).
nephrotic syndrome (3 papers, 2014 to 2024). A collection of symptoms that include severe edema, proteinuria, and hypoalbuminemia; it is indicative of renal dysfunction. "Plasma creatinine and cystatin C were statistically significantly elevated in diabetic microalbuminuria and nephrotic syndrome patients compared with diabetic normoalbuminuria and control groups (P < 0.001) for both." (PMID 24876663, 2014).
pancreatic cancer (3 papers, 2022 to 2024). "Participants with a diagnosis of pancreatic cancer are associated with higher cystatin C (adjusted OR 2.15), eosinophil count (adjusted OR 1.41) and White ancestry (adjusted OR 2.51 compared to Asians)." (PMID 38263244, 2024). "This study aimed to evaluate the usefulness of the serum creatinine/cystatin C (Cr/CysC) ratio as a prognostic factor after pancreatic surgery in patients with pancreatic cancer." (PMID 37663967, 2023). "This study evaluated the usefulness of the serum creatinine/cystatin C (Cr/CysC) ratio as a prognostic factor after pancreatic surgery in patients with pancreatic cancer." (PMID 37663967, 2023). "Besides, we have introduced two biologically relevant triplets, namely Klk1 and {Gh1, Cst3} and Lamc2 and {Dhps, Ccr7}, which may be specifically involved in the onset of pancreatic cancer." (PMID 35180880, 2022).
pancreatitis (3 papers, 2013 to 2025). Inflammation of the pancreas. "We analysed the presence and prevalence of CST3 sequence variants in a cohort of pancreatitis patients and healthy controls." (PMID 39962054, 2025). "The ratio of uncut CST3 to processed CST3 changed significantly in favour of the processed variant after induction of pancreatitis." (PMID 39962054, 2025). "Larger cohort studies could clarify whether genetic variants in the CST3 gene are associated with the occurrence of pancreatitis." (PMID 39962054, 2025). "By necessity, the CST3-mediated inhibition of CTSB needs to be overcome for CTSB to activate trypsinogen during pancreatitis." (PMID 39962054, 2025). "Here, the authors show that cystatin C (CST3) regulates the activity of cathepsin B during pancreatitis in a pH dependent manner." (PMID 39962054, 2025). "Animal data as well as investigations of human samples suggest that, during pancreatitis, the lysosomal cysteine protease inhibitor CST3 undergoes redistribution into the zymogen-containing secretory compartment together with CTSB and CTSL." (PMID 39962054, 2025). "The disease severity marker serum amylase was higher 1 h and 24 h after induction of pancreatitis in Cst3−/− mice, and intrapancreatic trypsinogen activation was increased 1, 8 and 24 h after the onset of pancreatitis, while the activity of chymotrypsin was elevated at 1 h and 8 h." (PMID 39962054, 2025). "Now we were interested if we could observe a degradation of CST3 in the ZG-Fraction of mice 1 h after onset of pancreatitis." (PMID 39962054, 2025). "Multiple proteases become activated during pancreatitis which may cleave CST3." (PMID 39962054, 2025). "Nevertheless, in our sequencing analysis of 739 pancreatitis patients, we could not identify genetic variations in the CST3 gene that were significantly associated with chronic pancreatitis." (PMID 39962054, 2025). "In the zymogen fraction from Cst3−/− animals we observed significantly increased activities of CTSB and CTSL during pancreatitis, in comparison to control animals." (PMID 39962054, 2025). "Taken together these findings suggest processing of CST3 in the zymogen granule fraction during pancreatitis which affects its inhibitory capacity for CTSB but not for CTSL." (PMID 39962054, 2025). "Urinary accumulation of cystatin C, a marker of AKI, was detected by dot blot analysis in 3 out of 8 urine samples of pancreatitis animals, but not in control animals." (PMID 36300116, 2022).
rhabdomyolysis (3 papers, 2015 to 2023). Necrosis or disintegration of skeletal muscle often followed by myoglobinuria. "Consistent with this hypothesis, a recent publication described a group of eight military recruits hospitalized with severe exertional rhabdomyolysis with normal values of SCr and cystatin C but significant increases in serum NGAL, suggesting renal stress, as occurred in the present study." (PMID 30399190, 2018). "However, we did not observe an association of changes of cystatin C levels and CRP, NT-proBNP or CK after the race among our runners that would indicate a substantial inflammatory trigger, acute cardiorenal syndrome or rhabdomyolysis, respectively, as causes for the altered renal function." (PMID 25889047, 2015).